TLR7 (toll like receptor 7)
Diseases named in the same sentence as TLR7 in open-access papers (continued):
Sharing a sentence is not in itself a finding about the gene and the disease.
lupus (continued). "Several studies have shown that the expression of two copies of Tlr7 or Tlr8 alone was sufficient to induce autoimmunity in mice, whereas mice deficient in Tlr7 with a genetic background predisposing to lupus are significantly protected against autoimmunity." (PMID 33498655, 2021). "Anti-TLR7 mAb abolished this lupus-associated increase in patrolling monocytes in the circulation, spleen, and glomeruli." (PMID 34868046, 2021). "We found a disease-associated increase in Ly6Clow patrolling monocytes that expressed high levels of TLR7 and had upregulated expression of lupus-associated IL-10, CD115, CD31, and TNFSF15 in NZBWF1 mice." (PMID 34868046, 2021). "Here we report that TLR7 signaling drives the development of SS since TLR8-deficient (TLR8ko) mice that develop lupus due to increased TLR7 signaling by dendritic cells, also develop an age-dependent secondary pathology similar to associated SS." (PMID 34108972, 2021). "Lupus-associated TLR7-dependent monocytosis has been identified in the Yaa mouse model of lupus, in which TLR7 is hyperactivated due to its gene duplication." (PMID 34868046, 2021). "In a TLR7-induced lupus mouse model, Ifnlr1-deficient mice displayed reduced skin and kidney inflammation as well as decreased immune complex deposition." (PMID 34769174, 2021). "A lupus-prone mouse strain, Y-linked autoimmune accelerator (Yaa), has a duplicate copy of the TLR7 gene that results in TLR7 hyperactivation, leading to lupus-like states." (PMID 34868046, 2021). "Autoantibodies and ongoing inflammation cause cellular and tissue damage that releases more lupus associated autoantigens, which can interact with TLR7 to further propagate cellular and humoral autoimmunity." (PMID 33613527, 2020). "TLR7 plays an important pathogenic role; it is required in B cells for the formation of autoantibodies and GCs in murine lupus models, and its overexpression dramatically enhances the development of autoimmunity." (PMID 33519824, 2020). "The second involves the Sle1b lupus susceptibility allele, either alone, which breaches B cell tolerance, or in the context of enhanced TLR7 signaling, which leads to full blown autoimmune disease." (PMID 33519824, 2020). "Studies have unveiled the promoted levels of TNF-α and C-C Motif Chemokine Ligand 5 (CCL5) mRNA provoked by TLR4 and TLR7 in spleen macrophages of lupus-susceptible mice." (PMID 32760274, 2020). "Lupus is far more prevalent in women than men and it is, therefore, of interest that the TLR7 and IRAK1 genes are X-linked in both humans and mice." (PMID 31694920, 2019). "Sle1b lupus mouse model where autoantibody formation is driven predominantly through the GC-pathway, TLR7 deficiency also reduces anti-DNA Abs." (PMID 31354738, 2019). "Increase in Tlr7 gene dosage in non-autoimmune mice promotes the development of a lupus-like disease, whereas, the deletion of the Tlr7 allele in lupus-prone mice eliminates anti-RNA auto-Abs and reduces disease pathology." (PMID 31231380, 2019). "In short, multiple lines of evidence demonstrate that TLR7 dose can increase lupus susceptibility in both mice and humans." (PMID 31998321, 2019). "This can affect expression of genes that are easily induced by type I interferon, one of them being TLR7, which is well-established as susceptibility factor in lupus development, particulary in the context of the R2−/− model and the Yaa autoimmune modifier." (PMID 31681326, 2019). "The duplication of Tlr7 is demonstrated to be required to accelerate autoimmunity in lupus susceptible male mice." (PMID 31501466, 2019). "A loss of function Slc15a4 mutation ameliorates murine lupus and impairs interferon production mediated through TLR7 stimulation." (PMID 31001245, 2019). "A powerful example of X-linked dosage involvement comes from the BXSB murine lupus model, where the duplication of the X-linked Toll-Like Receptor 7 (Tlr7) gene aggravates autoimmunity in male mice." (PMID 31501466, 2019).
lupus (continued). "Mice that overexpress Tlr7, either as a transgene or in the context of the yaa mutation, have increased GCs on lupus-prone B6.Sle1 or B6.Sle1b backgrounds." (PMID 28278279, 2017). "To elucidate the role of the tissue-resident CD8+ T cells in lupus-prone mice, we bred TLR7[Tg] animals to germ-line deficient beta-2-microglobulin (β2m[KO]) animals." (PMID 28098193, 2017). "Extra copies of the Tlr7 gene drive lupus-like disease; whereas lupus-prone Tlr7-deficient mice develop attenuated disease symptoms." (PMID 28506291, 2017). "It has been reported that miRNA-3148 modulates the differential gene expression of the SLE- (systemic lupus erythematosus-) associated TLR7 (toll-like receptor 7) variant, and TLR7 mediates relaxation of airways through nitric oxide production." (PMID 28904974, 2017). "Deficiency of Tlr7 leads to complete abrogation of lupus disease in some murine lupus models while deficiency of Tlr9 enhances its severity." (PMID 27228057, 2016). "Using the NZB/W F1 murine lupus model, we unraveled a miR-155-associated hyperactive TLR7 response in BM-derived pDCs after the onset of lupus." (PMID 27509492, 2016). "In essence, the current study highlights the elevated pDC responses to TLR7 stimulation in lupus and suggests a potentially pathogenic role mediated by miR-155." (PMID 27509492, 2016). "Tlr7 is widely considered to be the genetic driver of overt SLE-like disease in the presence of other lupus susceptibility alleles in mice and genome wide association studies identified TLR7 as a risk factor for SLE in humans." (PMID 27050763, 2016). "The presence of at least one Tlr7 allele has previously been shown to be necessary for an optimal GC response to viral infection and for spontaneous GC activation in lupus prone mice." (PMID 25794167, 2015). "Lupus-prone mice deficient in TLR7 exhibited an amelioration of the disease including a decrease in serum autoantibody production (e.g., anti-Sm/RNP autoantibody), negative regulation of lymphocyte activation, and reduced severity of lupus nephritis." (PMID 26110387, 2015). "TLR7-overexpressing mice develop severe inflammatory kidney disease and increased mortality, whereas disease is ameliorated in TLR7-deficient lupus mice." (PMID 26322049, 2015). "Intriguing findings have been obtained from TLR8 deficient lupus-prone Nba2.Yaa mice, in which accelerated lupus nephritis and splenomegaly is observed, together with enhanced response to TLR7 ligation." (PMID 26068236, 2015). "Two recent reports have suggested that the CD11b lupus risk allele causes an impaired adhesion/phagocytosis and abnormal cytokine modulation after TLR7/8 stimulation in monocytes." (PMID 23451151, 2013). "For example, systemic lupus erythematosus was found to be associated with variation in TLR7 and Crohn’s disease and ulcerative colitis with variation in TLR8." (PMID 22857391, 2012). "Toll-like receptor 7 (TLR7) is involved in host innate immunity against pathogens, and its aberrant activation is linked to the development of systemic lupus erythematosus (SLE, also called “lupus”)." (PMID 22952664, 2012). "In another study, Sigirr deficiency is found to aggravate hydrocarbon oil-induced lupus, possibly due to hyperactivation of DCs by TLR7-mediated signal." (PMID 22952899, 2012). "Consistent with the in vitro finding, in vivo results with Tlr7-deficient lupus-prone mice verify the pathological significance of TLR7 in SLE." (PMID 22952899, 2012). "TLR7 and -9 activations are associated with lupus, and the TLR7 and -9 dual antagonists alleviate lupus pathogenesis." (PMID 22952664, 2012). "Autoantibodies directed against this complex are associated with both human and murine lupus, and the RNA component can serve as an endogenous ligand for TLR7." (PMID 19624844, 2009).
lupus (continued). "Altered dosage of Tlr7 results in lupus‐like phenotypes in mice, as the Yaa mouse model contains a Y‐linked autoimmune accelerating (Yaa) locus consisting of 16 X‐linked genes, including Tlr7, translocated onto the Y chromosome." (PMID 41574968, 2026). "In humans, gain-of-function mutations of TLR7 result in lupus-like monogenic diseases." (PMID 40910948, 2026). "Indeed, TLR7 overexpression induces systemic autoimmunity in mice, and gain-of-function mutations in TLR7 are a cause of human lupus." (PMID 41178711, 2025). "Such increased expression of several X chromosome-linked genes has been proposed in lupus, allowing certain immune-related genes such as TLR-7, TASL, CD40 ligand (CD40L), and Bruton’s Tyrosine Kinase (BTK) to be expressed from both X chromosomes in female cells." (PMID 41283475, 2025). "This mouse strain develops a severe form of murine lupus due to interactions between the y-linked autoimmune accelerator (yaa; Y chromosome-linked autoimmune acceleration) locus encoding TLR7 on the Y chromosome and other autoimmune disease alleles in the BXSB genome." (PMID 40710333, 2025). "To investigate the causal role of TLR7 in lupus-associated pain, we examined whether intrathecal administration of the TLR7 blocker ODN 2088 attenuates hind paw hypersensitivity to radiant heat in MRL/lpr mice." (PMID 41511304, 2025). "However, a number of studies in a mouse model of lupus have shown that TLR7 plays a pathogenic role in the pathogenesis of lupus, while TLR9 plays a protective role in the pathogenesis of lupus." (PMID 38429401, 2024). "The B6.Sle1yaa lupus model is driven by the Sle1 lupus susceptibility locus derived from lupus-prone NZB2410 mice in combination with the Y chromosome autoimmune accelerator locus whose effects are attributed to Tlr7 duplication." (PMID 38860651, 2024). "Rare genetic variants in toll-like receptor 7 (TLR7) are known to cause lupus in humans and mice." (PMID 38831104, 2024). "It was recently reported that polymorphisms in TLR7 are related to the development of lupus." (PMID 37894915, 2023). "An extensive body of literature demonstrates that TLR7 activation is pathogenic in the context of lupus, and emerging studies indicate that TLR7 may also mediate pathology in pSD." (PMID 39916928, 2023). "Within this relationship, TLR7-mediated lupus inflammation affects the gut-associated B cell response, the epithelial barrier integrity, and the systemic humoral response to commensals, altering the immune response that may fuel autoimmunity." (PMID 37346043, 2023). "Human systemic lupus erythematosus, the etiology of which was previously unknown, has been found to be caused by a TLR7 variant with a gain-of-function that enhances viral RNA sensing and thereby activates autoimmunity." (PMID 37871107, 2023). "Thus, in a lupus model where the TLR7/IFN-I axis is implicated in the development of autoimmunity, BAFF-producing DCs, MOs and Nphs each contribute to the induction of auto-Abs." (PMID 36923413, 2023). "Tlr7 polymorphisms and copy number have been associated with lupus susceptibility, and it would be of great interest to evaluate whether these genetic variations are associated with leaky gut and/or gut dysbiosis." (PMID 35795671, 2022). "Here we describe human systemic lupus erythematosus caused by a TLR7 gain-of-function variant." (PMID 35477763, 2022). "Moreover, deletion of TLR7 in lupus prone male mice bearing the Y chromosome-linked autoimmune accelerating (Yaa) locus that harbors 17 genes (including TLR7), demonstrated that TLR7 gene duplication was the cause for the development of lupus in these mice." (PMID 36389822, 2022). "An upregulated TLR7 signaling increase gut permeability, therefore, high fat diet may cause more severe gut leakiness in people genetically predisposed to lupus." (PMID 35795671, 2022).
lupus (continued). "Moreover, the overexpression of TLR7 due to the duplication of the Yαα (Y-chromosome-linked autoimmune acceleration) locus leads to the exacerbation of autoimmunity in murine lupus." (PMID 36359340, 2022). "Dysregulated functions of TLRs within the endosomal compartment, including TLR7/9 trafficking, may cause systemic lupus erythematosus (SLE)." (PMID 34884569, 2021). "We analysed sera from TLR7-, TLR9-, and TLR7/TLR9-double deficient lupus-prone MRL/lpr-mice." (PMID 34521462, 2021). "Of these, TLR7 has been most closely associated with disease pathogenesis in mouse lupus models." (PMID 34197340, 2021). "Furthermore, enhanced IFNα production was associated with increased TLR7 expression in the late endosomal/lysosomal compartment in lupus pDCs." (PMID 33633744, 2020). "Mouse studies suggest that Treml4 potentiates Toll-like receptor 7 (Tlr7) signaling in a model of systemic lupus erythematosus and genetic Treml4 deficiency protects animals from lupus-associated kidney failure, increased levels of inflammatory cytokines, and autoantibodies." (PMID 32292401, 2020). "Interestingly, deficiency of IFNγR in TLR7 overexpressing lupus-prone mice rescued B10 cells from TLR7-mediated reduction." (PMID 32849556, 2020). "Given that susceptibility to infections is one of the primary causes of morbidity and mortality in lupus patients, we evaluated splenic leukocytes to assess their ability to respond to viral and bacterial infections by using TLR7 and TLR9 agonists in vivo as a model of sterile inflammation." (PMID 32251357, 2020). "TLR7 duplication on the Y chromosome (Yaa locus) causes male-specific lupus in BXSB mice." (PMID 31998321, 2019). "Previous studies strongly support the pathogenic role of TLR7 in murine lupus." (PMID 31231380, 2019). "This may contribute to the prevalence of lupus in women; recall that duplication of the tlr7 gene in mice causes lupus to develop spontaneously." (PMID 31694920, 2019). "Likewise, overexpression of TLR7 causes development of lupus, and deficiency of TLR7 in lupus-prone MRL/lpr mice ameliorates disease." (PMID 31998321, 2019). "Moreover, it is important to know if these suppressive effects of IRAK4 elimination on TLR7-dependent lupus-traits are due to the loss of susceptibility loci resulting from the introduction of B6-nonautoimmune background into the F2 progeny." (PMID 31354711, 2019). "Indeed, TLR8-deficiency in mice on the C57BL/6 background leads to lupus development due to increased TLR7 expression and signaling by DCs." (PMID 31552019, 2019). "Importantly, overexpression of TLR7 has been shown to increase susceptibility to autoimmunity and has a role in disease pathogenesis in mouse models of lupus." (PMID 29988398, 2018). "Finally, we demonstrate that enhanced IFN-α production by TLR7-stimulated pDCs was associated with increased retention of TLR7 in late endosome/lysosome compartments in lupus pDCs." (PMID 29052537, 2017). "Many studies in lupus models have indicated a pathogenic role of TLR7 during lupus development." (PMID 26068236, 2015). "Systemic lupus erythematosus is an autoimmune disease in which recognition of endogenous ssRNA and dsDNA by TLR7 and TLR9 is an important pathogenic step for the induction of the IFN Signature and the production of autoantibodies against many self-antigens, including dsDNA." (PMID 24489947, 2014). "Overexpression of TLR7 causes severe lupus in multiple mouse models of SLE." (PMID 25538618, 2014). "This notion is further supported by observations that genes encoding products directly involved in TLR and IFN signaling pathways constitute a majority of genetic risk factors for SLE and that increased gene dosage of TLR7 directly results in lupus manifestation in vivo." (PMID 25077037, 2014). "Similarly, genetic modifications that lead to a duplication of the TLR7 gene or over-expression of transgenic TLR7 are associated with exacerbated lupus-like symptoms in murine models." (PMID 23908972, 2013).
lupus (continued). "To examine whether the TLR7-LMP1 relation is operative in vivo, we have examined PBMC from lupus patients because TLR7 activation is associated with lupus pathogenesis." (PMID 22952664, 2012). "In contrast, TLR7-deficient mice developed attenuated lupus symptoms." (PMID 23316484, 2012). "Indeed, the translocation of the X-linked TLR7 gene to the Y-chromosome has been documented to facilitate the development of fatal lupus in mice with numerous immunological aberrations, hence constituting disease genes for murine lupus." (PMID 20981241, 2010). "As TLR7 has restricted cell distribution in humans (plasmacytoid DCs and B cells) and has been linked to lupus pathogenesis in mice, we next tested the ability of class R and B INH-ODNs to block TLR7-induced activation of macrophages, DCs, AM14 B cells, and primary mouse B cells." (PMID 19476613, 2009). "RNA activation of TLR7 on B cells and plasmacytoid dendritic cells has been particularly strongly associated with lupus pathogenesis, based on its role as the genetic risk gene for a murine model of inherited lupus and its ability to induce lupus-associated type I interferon production." (PMID 18560522, 2008). "Recent studies, including reports of rare monogenic Toll-Like Receptor 7 (TLR7) gain-of-function mutations, have established TLR7 as a causal driver in a subset of human systemic lupus erythematosus (SLE) cases." (PMID 41869359, 2026). "Gain-of-function (GOF) variants in human TLR7 have recently been reported in 11 cases, six of which were diagnosed with systemic lupus erythematosus (SLE)." (PMID 41743833, 2026). "Responses of TLR7 to self-derived ssRNA have been implicated in the development of autoimmune diseases, such as systemic lupus erythematosus (SLE)." (PMID 40910948, 2026). "Similarly, autoimmune diseases such as Sjögren’s syndrome and Lupus, which are characterized by the production of antinucleic acid antibodies (ANAs), are associated with chronic activation of the TLR-7 pathway, leading to sustained inflammation and tissue damage." (PMID 40574053, 2025). "Unc-93 homolog B1 variants have been shown to specifically underlie TLR7-dependend early onset, as well as childhood systemic lupus erythematosus (SLE) by regulating TLR7 sorting and stability at the endosomal compartment." (PMID 40102400, 2025). "Notably, gain-of-function TLR7 mutations promote lupus in mice and humans." (PMID 40794441, 2025). "The pathogenesis of systemic lupus erythematosus (SLE) is linked to the differential roles of toll-like receptors (TLRs), particularly TLR7, TLR8, and TLR9." (PMID 38791389, 2024). "The functional relevance of TLR7 gene polymorphism rs3853839 (C/G) was previously demonstrated in systemic lupus erythematosus (SLE), where G-allele carriers had increased TLR7 mRNA expression and more enhanced IFN production than C-allele carriers." (PMID 38850110, 2024). "More recently, variants in UNC93B1 that disrupt degradative sorting of TLR7 have also been shown to cause human lupus, underscoring the importance of this pathway in human SLE." (PMID 38866437, 2024). "Interestingly, and consistent with our data on decreased T-bet expression and B cell proliferation in NAS-Tlr deficient mice, a recently described lupus-inducing TLR7 gain-of-function mutation shows both increased survival/proliferation and T-bet induction in B cells after IgM crosslinking." (PMID 38336876, 2024). "Among the innate immune signaling molecules, polymorphisms of Toll-like receptor 7 (TLR7) were reported to have a significant association with the development of SLE, and the epicutaneous application of TLR7 induced lupus-like disease in mice." (PMID 35371102, 2022). "In this context we have shown previously that TLR8-deficiency in C57BL/6 mice leads to lupus development due to increased TLR7 expression and signaling by DCs, and that this phenotype can be exacerbated under high fat diet conditions due to the additional increase of TLR7 signaling." (PMID 34108972, 2021).